H2BC17 (H2B clustered histone 17)
Description:
Core component of nucleosome. Nucleosomes wrap and compact DNA into chromatin, limiting DNA accessibility to the cellular machineries which require DNA as a template. Histones thereby play a central role in transcription regulation, DNA repair, DNA replication and chromosomal stability. DNA accessibility is regulated via a complex set of post-translational modifications of histones, also called histone code, and nucleosome remodeling.
Synonyms: H2B/n; H2BFN; HIST1H2BO; H2B.2; dJ193B12.2
Tractability: PROTAC: UniProt records ubiquitination sites on it; ubiquitination databases record sites on it.
Gene: Protein-coding gene on chromosome 6 (27,893,425 to 27,893,891, forward strand). Ensembl gene ENSG00000274641.
Subcellular location: Nucleus; Chromosome
Subcellular location (Human Protein Atlas): Nucleoplasm; Cytosol
Pathways (Reactome):
Gene expression (Transcription): B-WICH complex positively regulates rRNA expression; DNA methylation; ERCC6 (CSB) and EHMT2 (G9a) positively regulate rRNA expression; MLL4 and MLL3 complexes regulate expression of PPARG target genes in adipogenesis and hepatic steatosis; NoRC negatively regulates rRNA expression; PRC2 methylates histones and DNA; RNA Polymerase I Promoter Escape; RNA Polymerase I Promoter Opening; RUNX1 regulates genes involved in megakaryocyte differentiation and platelet function; RUNX1 regulates transcription of genes involved in differentiation of HSCs; Regulation of endogenous retroelements by KRAB-ZFP proteins; Regulation of endogenous retroelements by Piwi-interacting RNAs (piRNAs); Regulation of endogenous retroelements by the Human Silencing Hub (HUSH) complex; SIRT1 negatively regulates rRNA expression; Transcriptional regulation by small RNAs
Chromatin organization: CHD1 and CHD2 subfamily; CHD6, CHD7, CHD8, CHD9 subfamily; ChAHP complex assembly; HATs acetylate histones; HDACs deacetylate histones; Interaction of NuRD complexes with transcription factors; NuRD complex assembly
DNA Repair: Cleavage of the damaged purine; Cleavage of the damaged pyrimidine; Nonhomologous End-Joining (NHEJ); Processing of DNA double-strand break ends; Recognition and association of DNA glycosylase with site containing an affected purine; Recognition and association of DNA glycosylase with site containing an affected pyrimidine; Recruitment and ATM-mediated phosphorylation of repair and signaling proteins at DNA double strand breaks
Cell Cycle: Condensation of Prophase Chromosomes; Deposition of new CENPA-containing nucleosomes at the centromere; G2/M DNA damage checkpoint; Inhibition of DNA recombination at telomere; Packaging Of Telomere Ends
Developmental Biology: Activation of anterior HOX genes in hindbrain development during early embryogenesis; Chromatin modifications during the maternal to zygotic transition (MZT); Replacement of protamines by nucleosomes in the male pronucleus; Transcriptional regulation of granulopoiesis
Disease: Defective pyroptosis; Dengue Virus-Host Interactions
and 18 more pathways
Gene Ontology:
Molecular function: protein binding; DNA binding; structural constituent of chromatin; protein heterodimerization activity
Biological process: antibacterial humoral response; antimicrobial humoral immune response mediated by antimicrobial peptide; chromatin organization; innate immune response in mucosa
Cellular component: nucleus; nucleoplasm; nucleosome; chromosome
Genetic constraint (gnomAD): Loss-of-function variants: 11 observed, 6.4 expected, observed/expected ratio (o/e) 1.72, 90% interval 1 to 1.95. That is too few expected variants to judge how well the gene tolerates losing a copy. Missense variants: 171 observed, 181.43 expected, observed/expected ratio (o/e) 0.94, 90% interval 0.83 to 1.07. Synonymous variants: 103 observed, 77.62 expected, observed/expected ratio (o/e) 1.33, 90% interval 1.13 to 1.56.
Homologues: Orthologues: chimpanzee H2BC17 (100% identical), macaque H2BC17 (100% identical). Paralogues in human: H2BC21 (99% identical), H2BC9 (99% identical), H2BC10 (98% identical), H2BC11 (98% identical), H2BC18 (98% identical), H2BC4 (98% identical), H2BC6 (98% identical), H2BC7 (98% identical), H2BC8 (98% identical), H2BC12 (98% identical), H2BC15 (98% identical), H2BC3 (98% identical), and 9 more.
Diseases named in the same sentence as H2BC17 in open-access papers:
H2BC17 is named in the same sentence as 7 diseases in open-access papers, as found by Europe PMC text mining. Sharing a sentence is not in itself a finding about the gene and the disease.
H2BC17 shares sentences with these, for which no sentence is quoted: cancer (5 papers); systemic lupus erythematosus (4); breast carcinoma (3); cervical cancer (1); gastric cancer (1); osteoporosis (1); Zika virus infection (1).